SIRT3 (sirtuin 3)
Diseases named in the same sentence as SIRT3 in open-access papers (continued):
Sharing a sentence is not in itself a finding about the gene and the disease.
cardiac hypertrophy (continued). "The maintenance of mitochondria sirtuin-3 attenuates both stress- and obesity-induced cardiac hypertrophy, highlighting the importance of sirtuin-3 and mitochondria functioning to the changes occurring in LVH." (PMID 31434333, 2019). "SIRT3 has been found to block development of cardiac hypertrophy and protect cardiomyocytes from oxidative stress-mediated cell death." (PMID 31116256, 2019). "Previous studies showed that overexpression of SIRT3 blocks cardiac hypertrophy whereas knockout of SIRT3 in aged mice promotes cardiac hypertrophy." (PMID 30873415, 2019). "In rodents, cardiac hypertrophy is attenuated by the inhibition of ROS and the induction of sirtuin-3." (PMID 31434333, 2019). "SIRT3 has been shown to block cardiac hypertrophy by deacetylating FOXO3a and upregulating the expression of FOXO3a target genes such as MnSOD and catalase, decreasing ROS generation." (PMID 30574122, 2018). "In contrast, SIRT3 overexpression in mice hearts protected against myocardial hypertrophy and fibrosis." (PMID 30647820, 2018). "Previous studies have found that SIRT3 has a close relationship with oxidative stress and myocardial hypertrophy." (PMID 30200365, 2018). "SIRT3 can also protect cardiomyocytes from oxidative stress-mediated cell damage and block the development of cardiac hypertrophy." (PMID 29643974, 2018). "Recent studies show that SIRT3 regulates energy metabolism, resists oxidative stress, and prevents cardiac hypertrophy." (PMID 29643974, 2018). "In response to transverse aortic constriction, SIRT3 KO mice developed a more severe cardiac hypertrophy accompanied by impaired cardiac function and fibrosis than WT animals." (PMID 30131726, 2018). "Our latest study verified that 4 weeks of DMY (250 mg/kg/day) intragastric administration attenuated transverse aortic constriction (TAC) induced myocardial hypertrophy via oxidative stress inhibition and sirtuin-3 (SIRT3) pathway enhancement." (PMID 30410442, 2018). "It highlighted a novel therapeutic target, SIRT3, for the protective effect of H2S against myocardial hypertrophy." (PMID 30647820, 2018). "Honokiol, a natural biphenolic compound derived from the bark of magnolia trees, blocks and reverses cardiac hypertrophy by activating SIRT3." (PMID 29643974, 2018). "Sirt3 was shown to promote autophagy in AngII-induced myocardial hypertrophy through the deacetylation of FoxO1 in mice." (PMID 29535606, 2018). "Overexpression of SIRT3 was able to prevent cardiac hypertrophy in response to phenylephrine or angiotensin II treatment in H9c2 cardiomyoblast cells and rat neonatal cardiomyocytes." (PMID 30131726, 2018). "Four weeks after a transverse aortic constriction, the ejection fraction in Sirt3-KO mice was lesser than that in wild-type mice, which was accompanied by an increase in cardiac hypertrophy and fibrosis." (PMID 29643974, 2018). "Our study firstly demonstrated that DMY effectively increased SIRT3 expression and activity during myocardial hypertrophy." (PMID 30200365, 2018). "Taken together, DMY ameliorated TAC induced myocardial hypertrophy in mice related to oxidative stress inhibition and SIRT3 pathway enhancement." (PMID 30200365, 2018). "In conclusion, DMY attenuates myocardial hypertrophy induced by transverse aortic constriction via oxidative stress inhibition and SIRT3 pathway enhancement in mice." (PMID 30200365, 2018). "Different pharmacological approaches to increase SIRT3 expression or to enhance SIRT3 activity were a potent strategy to attenuate myocardial hypertrophy and other cardiovascular diseases." (PMID 30647820, 2018). "We found that NaHS increased SIRT3 expression in the preventive effect on isoproterenol- (ISO-) induced myocardial hypertrophy." (PMID 30647820, 2018). "The role of mitochondrial protein acetylation in cardiac hypertrophy was confirmed in in vitro studies where activation or overexpression of SIRT3 prevented the development of cardiac hypertrophy." (PMID 30131726, 2018).
cardiac hypertrophy (continued). "The present results revealed that DMY up-regulated SIRT3 expression, enhanced antioxidant capacity, suppressed oxidative stress, and inhibited myocardial hypertrophy in mice after TAC." (PMID 30200365, 2018). "A recent study reported that Honokiol blocks and reverses cardiac hypertrophy in mice by activating mitochondrial SIRT3, subsequently increasing mitochondrial protein deacetylation." (PMID 28931882, 2017). "In contrast, STA‐mediated effects on cardiac hypertrophy were totally abrogated in SIRT3.KO mice suggesting that SIRT3 is required for the anti‐hypertrophic activity of STA." (PMID 28396567, 2017). "SIRT3 has been shown to be a negative regulator of cardiac hypertrophy, ROS production, apoptotic cell death, metabolism, and aging." (PMID 28396567, 2017). "In order to confirm the implication of SIRT3 in the anti‐hypertrophic effects of STA, we evaluated the effects of PIKfyve inhibition in SIRT3.KO mice treated with isoproterenol (ISO) to induce cardiac hypertrophy." (PMID 28396567, 2017). "We concluded that CD38 plays an essential role in cardiac hypertrophy probably via inhibition of SIRT3 expression and activation of Ca2+‐NFAT signalling pathway." (PMID 28296029, 2017). "Studies have shown that Sirt1 can protect the heart from external stress, inflammation and cardiac hypertrophy; Sirt3 and Sirt7 in the heart of the stress response process also plays an extremely important role." (PMID 28582407, 2017). "SIRT3‐knockout mice are prone to age‐related disorders like cancer, cardiac hypertrophy, and metabolic syndrome." (PMID 27686535, 2017). "Studies from other laboratories showed that increased level of intracellular NAD+ enhanced the activities of SIRT1 and SIRT3 33, which in turn, suppressed cardiac hypertrophy through the activation of Foxo3a‐dependent antioxidant defence mechanism." (PMID 28296029, 2017). "SIRT3 can also block cardiac hypertrophy by augmenting the activity of LKB1, an upstream kinase of AMPK." (PMID 28423723, 2017). "For example, SIRT3 has been shown to protect against oxidative stress, attenuate fatty acid accumulation in the heart, and prevent development of stress-induced cardiac hypertrophy." (PMID 28542596, 2017). "In contrast, overexpression of Sirt3 in mice hearts provides protection against cardiac hypertrophy and fibrosis." (PMID 29234485, 2017). "Taken together, these results indicate that PIKfyve inhibition reduces cardiac hypertrophy through mitochondrial SIRT3 activation." (PMID 28396567, 2017). "SIRT3 provides protection against cardiac hypertrophy, dyslipidaemia and cardiomyopathy, however, genetic ablation of SIRT3 have no impact on atherogenesis, suggesting distinctive effects of different sirtuins in atherosclerosis." (PMID 27249230, 2016). "Here, by inducing the Sirt3-knockout mice to myocardial hypertrophy with chronic angiotensin II infusion for four weeks, we determined the role of Sirt3 in myocardial hypertrophy and autophagy." (PMID 27880725, 2016). "In the current study, we investigated the role and specific mechanism of Sirt3 in myocardial hypertrophy and autophagy." (PMID 27880725, 2016). "The present study elucidates the critical role of Sirt3 in autophagy during pathological myocardial hypertrophy." (PMID 27880725, 2016). "In conclusion, our data shed new lights on the intrinsic connection among Sirt3-FoxO1, cardiac hypertrophy and autophagy." (PMID 27880725, 2016). "Taken together, these data indicated that Sirt3 attenuated AngII-induced myocardial hypertrophy by promoting the autophagic process." (PMID 27880725, 2016). "Altogether, these results revealed that Sirt3 activation is essential to improve autophagy flux by reducing the acetylation modification on FoxO1, which in turn alleviates myocardial hypertrophy." (PMID 27880725, 2016).
cardiac hypertrophy (continued). "Further interpretation of the interaction between Sirt3 and FoxO1 will deepen the comprehension of autophagy regulation and provide support for targeting autophagy as a new therapy for myocardial hypertrophy." (PMID 27880725, 2016). "Sirt1, Sirt3 and Sirt6 have also demonstrated to attenuate cardiac hypertrophy, and protect cardiomyocytes from aging and oxidative stress." (PMID 27690014, 2016). "Conversely, overexpression or pharmacological activation of SIRT3 was able to ameliorate or even block cardiac hypertrophy and interstitial fibrosis in response to pressure overload or hypertrophy agonist treatment." (PMID 27790619, 2016). "SIRT3 has also been reported to repress the activation of Akt in cardiac hypertrophy through ROS and relieve the disease symptoms." (PMID 26317998, 2015). "To further explore the role of SIRT3 in the development of cardiac hypertrophy, we subjected SIRT3-KO mice and their WT controls to TAC." (PMID 25748450, 2015). "This study was designed to investigate the role of SIRT3 in cardiac hypertrophy-related lipid accumulation." (PMID 25748450, 2015). "Sirt3 has been attracted much attention because it regulates cardiomyocyte apoptosis, survival and cardiac hypertrophy." (PMID 25311234, 2015). "It has been reported that chronic Angiotensin II infusion (3.0 mg/kg/day for 14 days) produce cardiac hypertrophy and dysfunction in SIRT3-KO mice." (PMID 25748450, 2015). "Sirt3−/− mice have baseline cardiac hypertrophy evident at 4 or 13 months of age, although data from others show no increase in the cardiac mass of Sirt3−/− mice at 5 months of age." (PMID 25228883, 2014). "In contrast, overexpression of Sirt3 blocks cardiac hypertrophy by suppressing reactive oxygen species (ROS) formation." (PMID 25192254, 2014). "So far, only one SIRT3 transgenic mouse model has been reported, in which cardiac expression of the short-form SIRT3 protects mice againist angiotensin II-induced or isoproterenol-induced cardiac hypertrophy and fibrosis." (PMID 24454908, 2014). "As these mice display cardiac hypertrophy and fibrosis as ageing progresses and under stressful conditions 14,21,36, we propose that SIRT3 functions as a stress-responsive protein." (PMID 25210848, 2014). "Sirt3 also plays a critical role in the regulation of mitochondria ROS formation in aging-related cardiac hypertrophy." (PMID 24039710, 2013). "Constitutively expressed Sirt3 was shown to reduce ROS in adipocytes, and the increased expression of Sirt3 protected myocytes from genotoxic and oxidative stress and blocked cardiac hypertrophy by activating antioxidant enzymes such as MnSOD and catalase." (PMID 21390294, 2011). "In the SIRT3−/− mice that survived, there was a high incidence of cardiac hypertrophy, based on the size of the hearts and the size of the left ventricle as measured by echocardiography." (PMID 21212461, 2010). "Canagliflozin SIRT3 activator has therapeutic effects on cardiac hypertrophy." (PMID 41567643, 2025). "However, in several age-related disease models, including pre-diabetes, cardiac hypertrophy, and atherosclerosis, the SIRT3/PGC-1α axis is disrupted, leading to diminished respiratory capacity and increased oxidative stress." (PMID 40799515, 2025). "Our previous work pointed out that SIRT3 agonists could relieve oxidative stress and improve mitochondrial structural integrity, thus alleviating cardiac hypertrophy 46-48." (PMID 38250153, 2024). "Moreover, nicotinamide weakened the effect of 2-APQC on relieving myocardial hypertrophy, indicating that the treatment of myocardial hypertrophy by 2-APQC was dependent on SIRT3 activation." (PMID 38744811, 2024). "Taken together, these results demonstrate that 2-APQC is a novel targeted small-molecule SIRT3 activator that alleviates myocardial hypertrophy and fibrosis by regulating mitochondrial homeostasis, which would shed new light on discovery of a potential drug candidate for HF treatment in the future." (PMID 38744811, 2024).
cardiac hypertrophy (continued). "Furthermore, miR-214 induces mitochondrial dysfunction by targeting Sirtuin 3 (SIRT3) and is involved in myocardial hypertrophy incited by angiotensin II (Ang II) in mice." (PMID 39564110, 2024). "Interestingly, it has been recently demonstrated that SIRT4 inhibits SIRT3-mediated MnSOD deacetylation, leading to an increase in ROS levels during cardiac hypertrophy." (PMID 37998340, 2023). "SIRT3 was reported to prevent cardiac hypertrophy by activating AMPK." (PMID 37558995, 2023). "Sirt3 inhibits Angiotensin II-induced myocardial hypertrophy by activation of autophagy." (PMID 36675125, 2023). "A growing body of evidence demonstrates that SIRT3 is essential for maintaining mitochondrial function by regulating acetylation modifications in hypertensive diseases, including endothelial dysfunction, cardiac hypertrophy, fibrosis, and heart failure." (PMID 37237500, 2023). "Furthermore, a couple of studies have emphasized the function of Sirt3 in attenuating cardiac hypertrophy by the activation of antioxidant enzymes, the suppression of ROS production, and the maintenance of mitochondrial function." (PMID 37760018, 2023). "A report has shown that HL could ameliorate cardiac hypertrophy by binding to Sirt3, activating it and increasing Sirt3 levels and its enzymatic activity." (PMID 35370645, 2022). "Since impaired energetics contribute to the development of cardiac hypertrophy, activating SIRT3-AMPK signaling may, at least in part, ameliorate myocardial metabolic dysfunction in hypertrophic hearts." (PMID 35369299, 2022). "Interestingly, mice subjected to transverse aortic constriction (TAC) surgery for 4 weeks developed cardiac hypertrophy and fibrosis associated with an increase in oxidative stress related to decreased SOD2 activity and SIRT3 expression." (PMID 35453408, 2022). "Thus, SIRT3 plays an indispensable role in preventing mitochondrial dysfunction and cardiac hypertrophy during aging." (PMID 35571098, 2022). "Honokiol has been identified as an activator of SIRT3, which directly enter into mitochondria and bind to SIRT3 to enhance its enzymatic activity, thereby protecting the heart from pressure overload and doxorubicin‐induced cardiac hypertrophy." (PMID 35171536, 2022). "It has been shown to inhibit angiotensin II-induced cardiac hypertrophy via SIRT3 activation." (PMID 35369299, 2022). "SIRT3 interacts with FOXO3a to activate antioxidant genes, such as MnSOD and catalase, the products of which can reduce the level of ROS and positively affect disorders such as interstitial fibrosis and cardiac hypertrophy." (PMID 35571098, 2022). "Sirt3 agonist HL could ameliorate cardiac hypertrophy by activating Sirt3 and improving fatty acid oxidation resulting in the inhibition of acute kidney injury induced by cisplatin." (PMID 35370645, 2022). "Elevated acetyltransferase p300 significantly contributes to SIRT3-deficiency-induced CFR as p300 acetyltransferase specific inhibitor C646 treated SIRT3 deficient mice show improved CFR, ejection fraction, fractional shortening, reduced cardiac hypertrophy, and fibrosis." (PMID 34831061, 2021). "In the present study, quercetin demonstrated a beneficial effect in attenuating cardiac hypertrophy in SHRs and Ang II-induced hypertrophic response in H9c2 cells, which was concomitant with improved mitochondrial function as well as increased SIRT3 expression both in vivo and in vitro." (PMID 34776960, 2021). "Therefore, acetyltransferase p300 plays a pivotal role in SIRT3 deficiency-induced endothelial dysfunction, CFR, cardiac hypertrophy and matrix remodeling." (PMID 34831061, 2021). "The role of SIRT3 in cardiac hypertrophy has been widely examined both in vivo and in vitro." (PMID 34776960, 2021). "Thus, pathologic cardiac hypertrophy is associated with decreased cellular NAD+ levels, and supplementation with NAD+ activates cardiac SIRT3 and blocks ANGII-induced hypertrophy." (PMID 34829803, 2021).
cardiac hypertrophy (continued). "Considering that FOS is upregulated during cardiac hypertrophy and heart failure, SIRT3 may have a cardioprotective effect through its histone deacetylase activity in the heart." (PMID 33806509, 2021). "However, it has been reported that discrepancy of the two SIRT3 isoforms existed in a cardiac hypertrophy model." (PMID 34795840, 2021). "SIRT3 knockout mice exhibited a more severe cardiac hypertrophy and fibrosis after Ang II infusion, and these mice also exhibited increased cardiomyocyte size with an upregulation of MYH6 expression, increased interstitial and perivascular fibrosis, and upregulation of α‐SMA expression." (PMID 34180125, 2021). "Among them, the role of SIRT3 in cardiac hypertrophy has attracted considerable attention." (PMID 34776960, 2021). "Of note, the compound licoisoflavone A reduces cardiac hypertrophy by upregulation of SIRT3." (PMID 33806509, 2021). "Furthermore, choline, an essential nutrient, ameliorates cardiac hypertrophy by regulating metabolic remodeling through the AMPK/SIRT3 pathway." (PMID 33806509, 2021). "In addition, exogenous NAD supplementation was shown to promote SIRT3 activation and attenuate Ang‐II‐induced cardiac hypertrophy by maintaining intracellular NAD levels." (PMID 33973685, 2021). "Pillai et al57 also revealed that Sirt3 could activate LKB1 by deacetylating LKB1 in mice with myocardial hypertrophy and then regulate AMPK phosphorylation to alleviate myocardial hypertrophy." (PMID 32281286, 2020). "Collectively, these results demonstrate that Sirt3 could be an endogenous negative regulator of cardiac hypertrophy, which protects hearts by suppressing cellular levels of ROS." (PMID 33014281, 2020). "Honokiol increases Sirt3 activity, thereby alleviating the severity of cardiac hypertrophy." (PMID 33014281, 2020). "Based on the fact that both SIRT3 and PARP-1 consume NAD+ to exert their functions, we hypothesized that SIRT3 could inhibit cardiac hypertrophy by repressing PARP-1 activation in cardiomyocytes." (PMID 32139662, 2020). "SIRT3 also deacetylates and activate Foxo3a to inhibit cardiac hypertrophy." (PMID 32139662, 2020). "We aimed to investigate whether LCZ696 protects against pathological cardiac hypertrophy by regulating the Sirt3/MnSOD pathway." (PMID 33014281, 2020). "Sirtuin 3 (SIRT3) is a type III histone deacetylase that inhibits cardiac hypertrophy." (PMID 32139662, 2020). "Indeed, Sirt3 was reported to attenuate cardiac hypertrophy and dysfunction induced by transverse aortic constriction through regulation of the acetylation of mitochondrial proteins." (PMID 32271823, 2020). "Sirt3 is necessary to prevent mitochondrial dysfunction and cardiac hypertrophy during ageing." (PMID 32765955, 2020). "In addition, overexpression of SIRT3 or exogenous administration of NAD+ can inhibit cardiac hypertrophy in mice." (PMID 32139662, 2020). "Compounds such as Honokiol that activate mitochondrial Sirt3, block and reverse cardiac hypertrophy in mice and show protective cardiac function could be candidates for testing in Snrk cmcKO mice." (PMID 32968716, 2020). "SIRT3-dependent autophagy also appears to play a role in cardiac hypertrophy." (PMID 31492861, 2019). "The use of HFD reduced SIRT3 level in WT mice, exacerbated oxidative stress in WT and SIRT3 KO mice that impaired hypoxia-inducible factor (HIF) signaling and reduced myocardial capillary density causing greater cardiac hypertrophy and dysfunction." (PMID 31265457, 2019). "Similarly, HKL treatment prevented and also reverted the development of hypertrophy and fibrosis, and the induction of hypertrophic markers, thus indicating that SIRT3 not only protects against cardiac hypertrophy but can also revert it." (PMID 30131726, 2018). "In mice, HNK prevents cardiac hypertrophy by activating mitochondrial Sirt3." (PMID 30116474, 2018).